MT2A (metallothionein 2A)
Description:
Metallothioneins have a high content of cysteine residues that bind various heavy metals; these proteins are transcriptionally regulated by both heavy metals and glucocorticoids.
Synonyms: MT-2; MT-II; MT2
Tractability: PROTAC: ubiquitination databases record sites on it.
Gene: Protein-coding gene on chromosome 16 (56,608,584 to 56,609,497, forward strand). Ensembl gene ENSG00000125148.
Pathways (Reactome):
Cellular responses to stimuli: Metallothioneins bind metals
Immune System: Interferon gamma signaling
Gene Ontology:
Molecular function: protein binding; metal ion binding; zinc ion binding
Biological process: cellular response to erythropoietin; cellular response to interleukin-3; cellular response to zinc ion; cellular response to cadmium ion; cellular response to copper ion; detoxification of copper ion; intracellular copper ion homeostasis; intracellular zinc ion homeostasis; negative regulation of growth
Cellular component: cytoplasm; cytosol; nucleus
Genetic constraint (gnomAD): Loss-of-function variants: 6 observed, 10.21 expected, observed/expected ratio (o/e) 0.59, 90% interval 0.32 to 1.16. The upper end of that interval is the gene's LOEUF score, 1.16, which puts it in group 5 of 6, group 1 being the genes least tolerant of losing a copy. Missense variants: 57 observed, 82.63 expected, observed/expected ratio (o/e) 0.69, 90% interval 0.56 to 0.86. Synonymous variants: 27 observed, 30.73 expected, observed/expected ratio (o/e) 0.88, 90% interval 0.65 to 1.21.
Homologues: Orthologues: macaque MT2A (97% identical), zebrafish mt2 (62% identical). Paralogues in human: MT1G (95% identical), MT1F (92% identical), MT1A (90% identical), MT1H (90% identical), MT1X (90% identical), MT1HL1 (89% identical), MT1B (85% identical), MT1M (80% identical), MT3 (70% identical), MT4 (64% identical), MT1E (56% identical).
Diseases named in the same sentence as MT2A in open-access papers:
MT2A is named in the same sentence as 112 diseases in open-access papers, as found by Europe PMC text mining. Sharing a sentence is not in itself a finding about the gene and the disease. The quoted sentences say what the papers report.
breast carcinoma (36 papers, 2010 to 2025). "MT2A is highly expressed in hypoxic tumor tissues compared to normoxic ones in breast cancer patients, among whom higher expression of MT2A is associated with a worse prognosis, and it is required for breast tumor growth." (PMID 41211480, 2025). "Other studies have shown an association between MT2A-5A/G SNP and an increased risk of breast cancer, prostate cancer and gastric adenocarcinoma." (PMID 36981043, 2023). "The genetic polymorphisms in MT2A (rs10636 and rs28366003) increases the risk of breast cancer in Chinese Han population." (PMID 33240582, 2020). "A specific isoform of this protein, MT-2A, has been widely studied as a poor prognostic factor in breast cancer, with its presence associated with more aggressive tumor behavior." (PMID 31936364, 2020). "We performed this case-control study, including 459 breast cancer (BC) patients and 549 healthy controls from Northwest China, to evaluate the associations between two common MT2A polymorphisms (rs10636 and rs28366003) and BC risk." (PMID 28228606, 2017). "MT2A over-expression is associated with cell proliferation in cancerous breast tissue, with significantly modified breast cancer risk, and cell cycle is inhibited through silencing MT2A." (PMID 27608012, 2016). "Our data suggest that the rs28366003 SNP in MT2A is associated with risk of breast cancer in Polish population." (PMID 23053628, 2014). "Taking into account the potential role of MT2A in breast carcinogenesis, we have analyzed an association between breast cancer and three known single nucleotide polymorphisms (SNPs) of MT2A gene." (PMID 23053628, 2014). "Up-regulation of MT2A, the most abundant of these, is associated with more aggressive breast cancer and poor prognosis, and it is reported that the over-expression of metallothioneins predicts resistance to doxorubicin." (PMID 20731868, 2010). "Previous study showed that TNBC showed the worst prognosis in breast cancer, this analysis indicated that higher expression of MT2A might be associated with a worse prognosis." (PMID 41211480, 2025). "Several analyzes suggested that, the rs28366003 in MT2A correlates with breast cancer risk." (PMID 32765800, 2020). "We carried out an association study to examine whether MT2A gene polymorphisms are associated with risk of breast cancer." (PMID 23053628, 2014). "One SNP in MT2A (rs28366003) showed a positive association with breast cancer." (PMID 23053628, 2014). "The upregulation of MMP‐9 through the activation of AP‐1 and NF‐κB is facilitated by MT‐2A, thereby promoting the invasion and migration of breast cancer cells." (PMID 39676279, 2024). "For example, MT2A is upregulated in osteosarcoma, breast cancer and prostate cancer, with carcinogenic roles, while it is downregulated in gastric carcinoma, hepatoma and lung cancer, with cancer suppression roles." (PMID 35642057, 2022). "Clinical studies have also correlated high expression of MTs with breast cancer, specially MT2A, which is overexpressed and modulates invasion and migration via MMP-9 activating signaling pathways such as AP-1 and NF-kB." (PMID 34572798, 2021). "On the one hand, MT2A is a pro-oncogene in breast cancer 27, prostate cancer 28, large B cell lymphoma 29, and adrenocortical cancer 30, and closely related with unfavorable prognosis of numerous malignant tumors." (PMID 34220318, 2021). "It is reported that MT2A promotes the migration and invasiveness of cancer cells in breast cancer and mucoepidermoid cancer by regulating MMP9 expression." (PMID 34572779, 2021). "For example, over-expression of MT2A is related with chemoresistance in ductal breast cancer, and predicts poor prognosis in non-small cell lung cancer." (PMID 34663301, 2021). "Specific MTs such as MT1F and MT2A have been found in greater numbers in cancer in stage 3 than in stage 1 and 2 when histological samples of breast cancer were analyzed." (PMID 34572798, 2021).
breast carcinoma (continued). "In breast cancer cells, the downregulation of MT-2A by siRNA results in the induction of growth arrest and apoptosis; however, the exact mechanism by which MT-2A influences cancer cell invasion in breast cancer has not been well explained." (PMID 30347787, 2018). "In contrast, the downregulation of MT in MCF-7 cells with an 18-mer antisense phosphorothioate inhibited growth and initiated apoptosis, suggesting a close involvement of the MT-2A isoform in the proliferative activity of breast cancer cells." (PMID 30347787, 2018). "Clinical studies have demonstrated that MT2A overexpression enhanced breast cancer cell invasion and migration via the upregulation of MMP-9 induced by the activation of the AP-1 and NF-κB signaling pathways." (PMID 30139373, 2018). "In the breast cancer MDA-MB-231 cells, their enhanced invasive properties, caused by the overexpression of the MT2A isoform, were associated with the increased expression of MMP-9." (PMID 25933064, 2015). "A number of studies have demonstrated increased MT2A expression in various human tumors, including breast cancer." (PMID 23053628, 2014). "Thus, our findings reveal the MT2A-copper-PKM2 axis as a potential therapeutic target to treat breast cancer." (PMID 41211480, 2025). "We examined the effect of MT2A in breast cancer cell proliferation." (PMID 41211480, 2025). "Altogether, these data suggested the pathological relevance of MT2A in breast cancer." (PMID 41211480, 2025). "At the current stage, in order to investigate the pathological relevance of hypoxia-responsive MT2A in breast cancer, we analyzed the human breast cancer single-cell RNA sequencing (scRNA-seq) dataset to examine the correlation between MT2A expression patterns and tumor hypoxic status." (PMID 41211480, 2025). "In conclusion, these results suggested that MT2A is essential for breast cancer growth." (PMID 41211480, 2025). "Accordingly, we extended this analytical framework of MT2A to investigate the pathological relevance of hypoxia-responsive PKM2 in breast cancer with the human breast cancer scRNA-seq dataset to examine the correlation between PKM2 expression patterns and tumor hypoxic status." (PMID 41211480, 2025). "A case–control study in the Chinese Han population indicated that the minor allele G of MT2A rs28366003 was related to an increased breast cancer risk." (PMID 36690679, 2023). "Metallothionein-2A, a member of the metallothioneins, could promote breast cancer cell invasion by increasing the expression level of MMP9." (PMID 28109307, 2017). "According to our present observation with MDA-MB-415 and ZR-75-1 cells, in endocrine-resistant breast cancers overexpressing MT2A, FtH, or Hsp70, rapalogues might enhance the autophagy-mediated relocation of these factors to the lysosomes, blunting LMP and further exacerbating drug-resistance." (PMID 33809171, 2021). "Interestingly, among the over-expressed genes, MT2A (metallothionein 2A) and CCNE1 (cyclin E1) are associated not only with breast cancer, but also with cadmium induction suggesting that the microarray analysis is identifying genes relevant to both cadmium exposure and breast cancer." (PMID 24376830, 2013). "In this regard, it has been shown that HIPK2 negatively regulates MT2A gene, whose mRNA transcript isoform appears to be associated with cell proliferation in invasive ductal cancer tissues and that, on the contrary, HIPK2 depletion correlates with MT2A up-regulation in MCF7 breast cancer cells." (PMID 20876941, 2010).
breast carcinoma (continued). "We clustered cancer cells from patients with different subtypes of breast cancer, and found that cancer cells from TNBC patients had the highest expression levels of MT2A." (PMID 41211480, 2025). "Most breast cancer cells (clusters 0–5) exhibited high levels of hypoxia‐related genes, including HSPA1A, MT2A, S100A11, MALAT1, and UBC." (PMID 39805002, 2025). "In MCF7 breast cancer cells, HIPK2 knockdown is correlated with metallothionein 2A (MT2A) up regulation." (PMID 26493598, 2015). "Therefore, we investigated the correlations between MT2A and PKM2 based on human breast cancer scRNA-seq dataset." (PMID 41211480, 2025). "The roles of MT1CP, MT1L, and MT2A in HCC are still unknown, while MT2A could promote breast cancer invasiveness and might play a suppressive role in gastric cancer through inhibition of the NK-κB signaling pathway." (PMID 35300417, 2022).
gastric cancer (21 papers, 2013 to 2024). A primary or metastatic malignant neoplasm involving the stomach. "As a clinical impact of Mt2a, it has recently been shown that attenuation of MT2A and IkB-α gene expression in human gastric epithelial cells is associated with a poor prognosis in gastric cancer patients." (PMID 36060520, 2022). "The downregulation of metallothionein 2A (MT2A), a stress protein is associated with poor prognosis in gastric cancer patients." (PMID 33390834, 2021). "Previous studies have shown that metallothionein 2A (MT2A) is downregulated in gastric cancer cells and exerts its anti-gastric cancer effect by binding to MZF1 to target NFKBIA23." (PMID 38443583, 2024). "In gastric cancer datasets, MT2A, TXNIP, FOS, RHOB, and GLUL emerged as the five most important mRNAs to predict exmiRs." (PMID 39495117, 2024). "This study investigated the correlation between the H. pylori virulence genes and ptk2 and mt2a genes expression in gastric antral epithelial cells of gastritis and gastric cancer patients with H. pylori infection." (PMID 36060520, 2022). "For example, MT2A is downregulated in gastric cancer and is related to the chemotherapy sensitivity of gastric cancer cells to docetaxel." (PMID 35642057, 2022). "Kaplan–Meier survival assays indicated that patients with a high expression level of MT2A in gastric cancer had a significantly better overall survival." (PMID 34572779, 2021). "On the contrary, higher levels of MT2A are associated with favorable outcome in patients with gastric cancer, and MT2A exerts anti-gastric cancer effects by complexing with MZF1 to target NFKBIA." (PMID 34663301, 2021). "It was reported that MT2A reduces the activity of NFκB and suppresses the malignant phenotypes in gastric cancer." (PMID 34572779, 2021). "In contrast, MT2A was also shown to suppress tumor progression by inhibiting NFκB in gastric cancer." (PMID 34572779, 2021). "On the other hand, the decreased expression level of MT2A in gastric cancer 31, liver cancer 32, and thyroid cancer 33 are negatively correlated with cancer mortality." (PMID 34220318, 2021). "Decreased MT2A expression was reported to be associated with advanced TNM stages, tumor differentiation, and poor outcomes in patients with gastric cancer." (PMID 30139373, 2018). "MT2A has been shown to regulate NF-κB pathway activation to participate in tumor progression in gastric cancer and colorectal cancer." (PMID 30139373, 2018). "DATS sensitized gastric cancer cells to docetaxel through the metallothionein 2A/NF-κB pathway, and enhanced G2/M phase cell cycle arrest and apoptosis." (PMID 28788092, 2017). "In this analysis of 171 normal gastric tissues, 118 intestinal metaplasia, and 684 primary gastric cancers, decreased MT2A was significantly correlated with poor prognosis." (PMID 23870553, 2013). "The elevated amplification of the miR-23a locus, in conjunction with other miRNAs, has been found to stimulate gastric cancer tumor growth while simultaneously diminishing the expression of the metallothionein 2A (MT2A) gene, a known tumor progression suppressor." (PMID 38002007, 2023). "HDAC inhibition as well as increased acetylation of the promoter for IκB-α regulator MT2A in gastric cancer cells provides one mechanism by which DATS may regulate NF-κB." (PMID 28788092, 2017). "Moreover, MT2A exerts its anti-gastric cancer effect by combining with MZF1 to target NFKBIA." (PMID 35642057, 2022). "MT2A expression was found to be decreased in gastric cancer cell lines and primary tumor tissues, and MT2A upregulation could significantly decrease cyclin D1 expression in gastric cancer cells, further indicating that MT2A upregulation could inhibit gastric cancer cell proliferation." (PMID 37091533, 2023). "It has been reported that DATS treatment can elevate both the mRNA and protein levels of MT2A, thereby improving the sensitivity of the anti-cancer drug, docetaxel (DOC), as well as the survival of gastric cancer patients." (PMID 33390834, 2021).
gastric cancer (continued). "Abundance of Metallothionein 2A (MT2A) exhibits in the gastric mucosal barrier, but its role in the progression of gastric cancer (GC) is still unclear." (PMID 23870553, 2013). "MT2A might be a chemosensitive indicator in gastric cancer (GC), and another study found that MT2A might play a role in suppressing tumor activity through inhibiting NF-κB and might be a prognostic biomarker and potential target for individual therapy of GC." (PMID 27608012, 2016). "Moreover, a study indicated that MT2A has tumor-suppressive activity through inhibiting nuclear transcription factor κB (NF-κB) signalling in gastric cancer patients; however, the functions and expressions of MT2A in bladder cancer have not been thoroughly scrutinized." (PMID 36009228, 2022).
prostate carcinoma (14 papers, 2015 to 2023). A carcinoma that arises from epithelial cells of the prostate gland. "Gene expression level of MT2A was also lower among the minor allele carriers compared to average expression reported among homozygotes for the major allele, while prostate cancer tissue recorded higher levels compared to normal prostate tissue." (PMID 36551962, 2022). "Levels of Zn, Cu, and Cd recorded from prostate cancer tissue too were higher among men carrying the minor allele G of the MT2A rs28366003 polymorphism." (PMID 36551962, 2022). "Forma studied the association between MT2A (rs28366003, rs1610216, and rs10636) and the risk of prostate cancer." (PMID 28228606, 2017). "And only the rs28366003 SNP in MT2A was observed to be correlated with the prostate cancer risk in Polish population." (PMID 28228606, 2017). "Frankly, although MT-1 and MT2A have been largely studied together, MT2A have specific functions in regulating autophagy and apoptosis, and increasing risk of prostate cancer, as well as ductal breast cancer." (PMID 27608012, 2016). "The only study on rs28366003 in MT2A was conducted in Poland and showed that this polymorphism may contribute to high risk of prostate cancer." (PMID 30036379, 2018). "We also determined if polymorphisms in several Zn-dependent genes (MT2A, MMP-1, MMP-2, MMP-7, MMP-13) contributed to prostate cancer risk." (PMID 30036379, 2018). "In this study we sought to analyze to what extent variations in serum Zn level and polymorphisms in MT2A, MMP-1, MMP-2, MMP-7 and MMP-13 are related to prostate cancer among Polish men." (PMID 30036379, 2018). "Additionally, inhibited MT2A expression resulted in cell death and apoptosis in prostate cancer cells." (PMID 37920509, 2023).
colorectal cancer (10 papers, 2018 to 2024). A primary or metastatic malignant neoplasm that affects the colon or rectum. "Overexpression of MT2A inhibits proliferation and migration of colorectal cancer cells as well as growth and metastasis of cancer cells." (PMID 39061894, 2024). "An immunostaining analysis showed that the MT and MT2A expression levels in the cytoplasmic region of the colorectal cancer cells were increased by CBD treatment." (PMID 38068944, 2023). "The expression profile of metallothionein 2A (MT2A) in colorectal cancer retrieved from TCGA, GEO and Oncomine database." (PMID 35642057, 2022). "Results from in situ, in vitro, and in vivo studies have suggested that MT2A is an antitumor gene in gastric and colorectal cancers." (PMID 36009228, 2022). "First, we found that MT2A was downregulated in colorectal cancer using TCGA, GSE and Oncomine databases." (PMID 35642057, 2022). "The present study showed that the MT2A expression level in colorectal cancer was correlated with tumor M stage." (PMID 35642057, 2022). "Cannabidiol was able to exert a therapeutic effect on colorectal cancer, and overexpression of MT1G and MT2A increased the number of dead cells and synergistically enhanced the anticancer effect of cannabidiol." (PMID 39061894, 2024). "MT2A knockdown enhances oxaliplatin sensitivity in HT29 OR cells MT2A interacts with BARD1/BRCA1 and positively regulates and promotes oxaliplatin resistance in colorectal cancer cells." (PMID 36466860, 2022). "Although the MT2A expression level in CRC may be related to tumor heterogeneity and further studies are needed to explore the reasons for this phenomenon, our results suggested that MT2A is a promising therapeutic target for colorectal cancer." (PMID 35642057, 2022).